BDNF (brain derived neurotrophic factor)
Diseases named in the same sentence as BDNF in open-access papers (continued):
Sharing a sentence is not in itself a finding about the gene and the disease.
injury (continued). "Thus, supplementation of n-3 PUFAs can normalize BDNF levels and reduce oxidative damage in traumatic brain injury model of rats." (PMID 30248907, 2018). "Thus, the rapid upregulation of BDNF and trkB make it likely that BDNF is the main neurotrophin mediating early motoneuron response to nerve injury." (PMID 30687012, 2018). "We wanted to determine whether endogenous BDNF is involved in the regulation of PACAP mRNA expression after nerve injury." (PMID 24968020, 2014). "A recent study has shown that using genetically modified MSCs to over-express BDNF mitigated hypoxic ischemic (HI) deficit by reducing brain infarct, preventing apoptosis, and reducing astrogliosis and inflammatory responses in a rat model of severe neonatal HI brain injury." (PMID 36986535, 2023). "Collectively, these findings suggest that the administration of BDNF gene-modified MSCs is insufficient, and further studies to determine the optimal strategies regarding the route, timing, and dose are warranted for their best therapeutic efficacy against severe neonatal HI brain injury." (PMID 34768827, 2021). "It should be mentioned here that nerve injury or other insults leading to neuropathic pain cause changes beyond chloride dysregulation in spinal neurons, and that the chloride dysregulation triggered by nerve injury may be more modest than modeled here by KCC2 blockade or intrathecal BDNF." (PMID 31742556, 2019). "When the BDNF-dependent driving force is lost, the baseline levels required to allow the development of a normal adaptation of central brain responses after cochlear injury may be lost." (PMID 26476841, 2016). "Brain-derived neurotrophic factor (BDNF) plays a prominent role in promoting axonal growth of motor and sensory neurons, and endogenous BDNF is required for peripheral nerve regeneration and remyelination after nerve injury; however, high doses of BDNF inhibited regeneration in acute nerve injury." (PMID 21931774, 2011). "A previous study investigated the striatal neurogenesis and subsequent functional recovery following chronic infusion of BDNF and Epidermal Growth Factor (EGF) in an animal model of hypoxic neonatal brain injury." (PMID 40895108, 2025). "Wuet al’s research concludes that supplementation of omega-3 fatty acids can restore cognitive function and normalize the action of BDNF, synapsin I, and CREB as well as oxidative damage after traumatic brain injury." (PMID 39810851, 2024). "Brain injury also damages the blood-brain barrier or alters its permeability, resulting in a significant increase in serum MBP and BDNF concentrations." (PMID 37645013, 2023). "Recently, Siebert and Osterhout indicated that neurotrophic factors, especially BDNF, GDNF, and NT-3, promote axonal regeneration after spinal trauma and have a profound effect on oligodendrocyte lineage cells." (PMID 37239968, 2023). "In our previous study, thrombin-preconditioned MSCs secreted higher level of BDNF and showed a more significant therapeutic effect for neonatal HIE-induced brain injury than did naïve MSCs." (PMID 35457266, 2022). "Following experimental traumatic brain injury in rats, a DHA-enriched diet for 12 days preserved brain-derived neurotrophic factor (BDNF) concomitant improved learning capability." (PMID 33255561, 2020). "The neuroprotective effects of BDNF are well-known, including against CORT-mediated damage in cellular and animal models of brain injury." (PMID 32570881, 2020). "The authors show that BDNF and NGF levels are significantly higher in the cerebrospinal fluid and plasma of children with severe traumatic brain injury, compared to the control group." (PMID 32987792, 2020). "Our previous study in experimental traumatic brain injury further showed that 7,8-DHF application induced BDNF mRNA upregulation through enhancing CREB activation in neurons." (PMID 31307481, 2019).
injury (continued). "Trophic factors, such as brain derived neurotrophic factor and neurotrophin 4/5, are known to improve RGC survival but only partially protect these cells from death after nerve injury." (PMID 27007653, 2016). "As SCFAs influence the immune system and differ in preterm infants with and without brain injury, we examined their effect on BDNF secretion in PBMCs stimulated with bacterial components." (PMID 40170375, 2025). "Molecular pathways such as cAMP, MAPK, JAK/STAT, ATF3/CREB, BMP/SMAD, AKT/mTORC1/p70S6K, PI3K/AKT, GSK-3β/CLASP, BDNF/Trk, Ras/ERK, integrin/FAK, RhoA/ROCK/LIMK, and POSTN/integrin are activated after nerve injury and are considered significant players in axonal regeneration." (PMID 36551942, 2022). "Engineered MSCs overexpressing BDNF were intracerebroventricularly administered directly into the left lateral ventricle of the brain, ultimately improving the neurological and cognitive functions of traumatic brain injury rats in the Morris water maze test compared to a negative control." (PMID 38399342, 2024). "In the in vivo neonatal HI brain injury animal model, short-term brain injury scores, long-term progress of brain infarct, and impaired behavioral function tests were significantly attenuated only with irradiated BDNF-eMSCs, but not with naïve MSCs transplantation." (PMID 34768827, 2021).
post-traumatic stress disorder (81 papers, 2011 to 2026). An anxiety disorder precipitated by an experience of intense fear or horror while exposed to a traumatic (especially life-threatening) event. "The search was restricted to articles published prior to December 2025, focusing on case-control studies investigating the association between BDNF DNA methylation and post-traumatic stress disorder (PTSD)." (PMID 41660208, 2026). "Previous studies have shown that the brain‐derived neurotrophic factor (BDNF) rs6265 G > A polymorphism is closely related post‐traumatic stress disorder (PTSD) risk." (PMID 33835731, 2021). "This study mainly aimed to explore the association between brain-derived neurotropic factor (BDNF) Val66Met polymorphism and posttraumatic stress disorder (PTSD) among flood survivors in China." (PMID 28589140, 2017). "Brain-derived neurotrophic factor Val66Met has been linked to a variety of psychopathologies, including major depressive disorder, bipolar disorder schizophrenia, and post traumatic stress disorder." (PMID 31496979, 2019). "A number of genes, including BDNF, are associated with risk for post-traumatic stress disorder (PTSD), and rs6265 is associated with the psychotic symptoms of PTSD." (PMID 35887357, 2022). "Conversely, significantly elevated BDNF levels have been observed in individuals with post-traumatic stress disorder." (PMID 41303216, 2025). "More broadly, others have found that cannabinoids prevent depressive-like behaviours, an effect that was accompanied by alterations in BDNF expression, in a rat model of posttraumatic stress disorder." (PMID 38555299, 2024). "We have observed a similar trend in our previous study, which focused on the difference in plasma BDNF concentrations between veterans with combat-related post-traumatic stress disorder (PTSD) and healthy controls." (PMID 36979505, 2023). "Apart from its role in AD, BDNF has also been shown to be decreased in neuropsychiatric disorders such as depression and post-traumatic stress disorder (PTSD)." (PMID 37446337, 2023). "Increased methylation of BDNF promoter genes has been observed in patients with borderline personality disorder and post-traumatic stress disorder." (PMID 34640441, 2021). "Patients with post-traumatic stress disorder (PTSD) who responded to therapy presented a raise in BDNF levels mostly when combined with physical activity." (PMID 32508690, 2020). "For instance, BDNF levels in adulthood are decreased following longer exposure to stress, posttraumatic stress disorder (PTSD)-like behavioral stress, or adverse early experiences." (PMID 31380440, 2019). "Basal BDNF in patients suffering from posttraumatic stress disorder was significantly lower than in healthy individuals." (PMID 26075212, 2015). "Interestingly, stress-induced BDNF dysregulation is brain region-specific, as observed in post-traumatic stress disorder (PTSD) in which BDNF mRNA is differentially downregulated in certain brain regions while being upregulated in others." (PMID 35955546, 2022). "In addition, stress and post-traumatic stress disorder (PTSD)-like behavior is connected to lower BDNF levels." (PMID 33477654, 2021). "This study investigates whether blood levels of BDNF in patients with post-traumatic stress disorder (PTSD) are different." (PMID 33152026, 2020). "The level of BDNF in the brain has been related to successful fear extinction, and peripheral BDNF has been shown to be positively related to the effectiveness of exposure-based treatment for post-traumatic stress disorder (PTSD) and panic disorder." (PMID 30885256, 2019). "The downregulation of BDNF levels in the CA1 sub-region of the hippocampus was correlated with responses in rats that resembled post-traumatic stress disorder (PTSD)." (PMID 37895171, 2023).
post-traumatic stress disorder (continued). "In a male rat model of post-traumatic stress disorder (PTSD), moderate exercise was shown to increase the expression of insulin-like growth factor-1 (IGF-1) and activate the BDNF/TrkB axis, which in turn stimulates the PI3K/Akt pathway." (PMID 41169370, 2025). "Similar changes in BDNF have been observed in post-traumatic stress disorder (PTSD)." (PMID 37259398, 2023). "On the other hand, some studies on the post-traumatic stress disorder (PTSD) model showed a positive correlation between arousals and BDNF expression in the medial prefrontal cortex, which might lead to altered behavior." (PMID 36768132, 2023). "The function of the hyperpolarization-activated cyclic nucleotide-gated channel 1 (HCN1) and the expression of brain-derived neurotrophic factor (BDNF) may be involved in the pathogenesis of post-traumatic stress disorder (PTSD)." (PMID 32198387, 2020). "T1-weighted structural magnetic resonance imaging, BDNF rs6265 genotyping through blood sampling, and clinical assessments including the childhood trauma questionnaire (CTQ) and posttraumatic stress disorder Checklist (PCL) were performed." (PMID 30988377, 2019). "Thus, pharmacological enhancement of E2 or BDNF/TrkB signaling may prove to be clinically relevant for the treatment of disorders in women involving maladaptive memories and behavioral inflexibility such as addiction or posttraumatic stress disorder." (PMID 31417375, 2019). "Here we investigated the role of DNA methylation of the brain-derived neurotrophic factor (Bdnf) gene in the therapeutic effects of ketamine in combination with extinction training in a mouse model of post-traumatic stress disorder (PTSD) induced by inescapable electric foot shocks (IFS)." (PMID 28473755, 2017). "The dysregulation, or aberrant regulation, of BDNF has also been identified as a vital mechanism of pathophysiology for stress-related psychiatric disorders, e.g., MDD, generalized anxiety disorder (GAD), post-traumatic stress disorder (PTSD), etc.." (PMID 40362507, 2025). "It was suggested that miR-15a-5p, let-7d-5p, miR-511-5p, and miR497a-5p, which target the two key post-traumatic stress disorder-related genes, FKBP5 and BDNF, were differentially modulated in the several brain regions of the post-traumatic stress disorder-related susceptible and resilient mice." (PMID 36430957, 2022). "A recent study by Sun and colleagues reproducing an ELS rat model of post-traumatic stress disorder (PTSD) using a maternal separation (MS) protocol and a subsequent single prolonged stress (SPS) procedure examined H3K9 acetylation (H3K9ac), HDAC2, and BDNF levels in the hippocampus." (PMID 39457754, 2024). "A considerable number of studies, at both the preclinical and clinical levels, have examined the relationship between BDNF and mental disorders, not just psychotic disorders but depression, anxiety disorder, post-traumatic stress disorder (PTSD), and Alzheimer’s disease." (PMID 27783051, 2016).
insomnia (79 papers, 2013 to 2025). A sleep disorder characterized by difficulty in falling asleep and/or remaining asleep. "In patients with insomnia, reduced levels of BDNF are associated with mood disorders such as anxiety and depression." (PMID 40144750, 2025). "A case–control study found that higher insomnia scores were associated with lower serum BDNF levels." (PMID 39555041, 2024). "This is unexpected, as other studies have found BDNF to be associated with sleep macrostructure and mentioned sleep qualities, insomnia in particular." (PMID 36984890, 2023). "Reduced serum BDNF levels have been observed in nurses experiencing insomnia, and BDNF gene polymorphisms, such as Val66Met and rs6265, have been implicated in moderating occupational distress among Chinese healthcare workers." (PMID 37822121, 2023). "One study reported associations between low levels of serum BDNF and self‐reported insomnia in middle‐aged adults." (PMID 36737401, 2023). "For example, poor sleep quality and disrupted circadian rhythms, including insomnia, short sleep duration, and circadian phase shifts have been associated with altered levels of serum brain derived neurotrophic factor (BDNF)." (PMID 34095836, 2021). "Based on subgroup analyses (no insomnia, sub threshold and clinical insomnia) an association between stress and BDNF was strongly pronounced in sleep healthy participants, while in subjects suffering from symptoms of insomnia this association was attenuated." (PMID 24146812, 2013). "Alterations in BDNF expression are linked to the onset and progression of neurological conditions, making it essential to evaluate nervous system health and conditions such as insomnia and memory disorders." (PMID 41011145, 2025). "Furthermore, research indicates that insomnia is linked to decreased levels of brain-derived neurotrophic factor (BDNF)." (PMID 41011145, 2025). "The mechanism by which LN19184 impacts sleep dynamics is unknown, but it may be related to the increased BDNF, as low levels of peripheral BDNF have been associated with insomnia." (PMID 41438191, 2025). "A recent meta-analysis concluded that insomnia is associated with decreased BDNF level." (PMID 36984890, 2023). "BDNF has an essential role in cognitive function and has been linked to clinical insomnia." (PMID 36062128, 2022). "In the same sample, we could already demonstrate an association between decreased serum BDNF levels and insomnia severity." (PMID 24146812, 2013). "Previously, we could show that an increase in severity of insomnia was associated with a decrease in serum BDNF levels of the same sample." (PMID 24146812, 2013). "Insomnia severity was associated with increased stress experience affecting serum BDNF levels." (PMID 24146812, 2013). "Additionally, a recent study by our group showed that insomnia is associated with decreased serum BDNF levels." (PMID 24146812, 2013). "Additionally, acupoint stimulation modulates the dysregulation of Bmal1 and Per2 mRNA expression associated with insomnia, normalises brain-derived neurotrophic factor (BDNF) level fluctuations, and mitigates endoplasmic reticulum stress in the medial septum of rats." (PMID 40270014, 2025). "For example, insomnia and abnormal sleep duration have been associated with lower circulating levels of BDNF, which protects against age-related brain atrophy, whereas both endurance exercise training and higher cardiorespiratory fitness have been shown to increase levels of BDNF." (PMID 36291294, 2022). "Lower BDNF levels lead to insomnia, a reduction of REM sleep time and lower slow-wave activity during the NREM sleep phase." (PMID 41010737, 2025). "Among the exploratory objectives were the analysis of symptoms such as hope and insomnia, as well as the assessment of biomarkers like baseline plasma BDNF levels, which have potential predictive value for treatment outcomes." (PMID 40423727, 2025).
insomnia (continued). "In contrast, sleep disturbances, particularly insomnia, significantly lower BDNF serum concentrations." (PMID 39997339, 2025). "A systematic review and meta-analysis found that peripheral BDNF was lower in insomnia patients than in controls." (PMID 39555041, 2024). "Other studies reported low BDNF levels to be related to more severe melancholic characteristics, psychomotor retardation or slowdown and insomnia." (PMID 38542503, 2024). "One study found a correlation between BDNF and sleep time, but the study participants were patients with insomnia symptoms." (PMID 38337587, 2024). "On the other hand, insomnia decreases BDNF levels, while an acute form of sleep deprivation increases them." (PMID 36984890, 2023). "On the other hand, previously, we have observed a positive correlation between the severity of insomnia and the BDNF protein concentration." (PMID 36984890, 2023). "Diseases characterized by chronic sleep insufficiency, such as insomnia, tend to feature low levels of BDNF." (PMID 36294343, 2022). "Acute and chronic stress has been associated with BDNF increase and decrease, respectively; thus, it is possible that BDNF levels change accordingly in insomnia and sleep deprivation." (PMID 36294343, 2022). "Sleep disturbances, a ubiquitous comorbidity in both mental and immune-related diseases, also affect the BDNF level: acute sleep deprivation increases whereas insomnia decreases the level of BDNF." (PMID 36294343, 2022). "Chronic sleep insufficiency, as observed in, e.g., insomnia, has been correlated with decreased BDNF levels." (PMID 36294343, 2022). "Another study on individuals with insomnia also confirmed the relationship between the severity of subjective sleep impairment and lower serum BDNF levels." (PMID 36498709, 2022). "One of the main findings of our study is that patients with OSA with poor sleep and insomnia have higher evening BDNF and proBDNF levels." (PMID 36498709, 2022). "Studies show that BDNF plays an essential role in sleep regulation, and any decrease in serum level of BDNF is directly related to insomnia." (PMID 34807519, 2021). "As a matter of fact, several conditions including stress, insomnia, fasting or caloric restriction, exercise, dietary supplements, and drugs were shown to alter serum BDNF levels." (PMID 33604378, 2021). "Further, the BDNF blood concentration of middle-aged adults with insomnia is lower than those of healthy adults, and the severity of insomnia is negatively correlated with BDNF value." (PMID 32723368, 2020). "Another disorder that has been shown its relation to BDNF and other NTs is sleep deprivation and insomnia." (PMID 33023629, 2020). "It has been demonstrated that patients with symptoms of insomnia showed notably decreased serum BDNF levels in comparison with healthy controls which this reduction significantly was related to the severity of insomnia." (PMID 33023629, 2020). "The changes in serum BDNF and GABA concentrations after the treatment were associated with the improvement of insomnia symptoms and the decreased cortical excitability as reflected by MEPs." (PMID 30609300, 2019). "In another study they investigated BDNF serum levels in 26 patients with insomnia and compared the results with a control group and found that insomniacs present decreased serum BDNF levels, when compared to control group." (PMID 29299044, 2017). "In the present study we found an interaction between stress and insomnia, which affects serum BDNF levels." (PMID 24146812, 2013). "We found a significant interaction between stress and insomnia with an impact on serum BDNF levels (F = 6.180, p = 0.017)." (PMID 24146812, 2013). "In summary, resveratrol can enhance neuronal health and improve insomnia by increasing BDNF levels." (PMID 40144750, 2025).